KRTAP9-8 (keratin associated protein 9-8)
Description:
In the hair cortex, hair keratin intermediate filaments are embedded in an interfilamentous matrix, consisting of hair keratin-associated proteins (KRTAP), which are essential for the formation of a rigid and resistant hair shaft through their extensive disulfide bond cross-linking with abundant cysteine residues of hair keratins. The matrix proteins include the high-sulfur and high-glycine-tyrosine keratins.
Synonyms: KAP9.8; KRTAP9.8
Tractability: No criterion of Open Targets' tractability assessment is met for any kind of drug.
Gene: Protein-coding gene on chromosome 17 (41,237,999 to 41,239,004, forward strand). Ensembl gene ENSG00000187272.
Pathways (Reactome):
Developmental Biology: Keratinization
Gene Ontology:
Molecular function: protein binding
Cellular component: cytosol
Genetic constraint (gnomAD): Loss-of-function variants: 10 observed, 12.32 expected, observed/expected ratio (o/e) 0.81, 90% interval 0.5 to 1.37. The synonymous counts are far from expectation, so gnomAD's model fits this gene poorly and the ratio says little. Missense variants: 197 observed, 190.54 expected, observed/expected ratio (o/e) 1.03, 90% interval 0.92 to 1.16. Synonymous variants: 94 observed, 66.02 expected, observed/expected ratio (o/e) 1.42, 90% interval 1.2 to 1.69.
Homologues: Paralogues in human: KRTAP9-2 (95% identical), KRTAP9-3 (93% identical), KRTAP9-9 (92% identical), KRTAP9-7 (89% identical), KRTAP9-4 (88% identical), KRTAP9-6 (81% identical), KRTAP9-1 (80% identical), KRTAP4-12 (50% identical), KRTAP4-9 (49% identical), KRTAP4-6 (48% identical), KRTAP4-11 (47% identical), KRTAP4-5 (45% identical), and 35 more.